AREG (amphiregulin)
Diseases named in the same sentence as AREG in open-access papers (continued):
Sharing a sentence is not in itself a finding about the gene and the disease.
chondrosarcoma (8 papers, 2015 to 2024). A malignant cartilaginous matrix-producing mesenchymal neoplasm arising from the bone and soft tissue. "Although a previous study has associated amphiregulin with tumor progression in chondrosarcomas, the immunoexpression of this antibody in ENC and its role in distinguishing ENC from LGC remain unclear." (PMID 34468540, 2021). "In addition, amphiregulin expression was directly associated with the histological grade of chondrosarcomas, with statistical significance observed between low- and high-grade lesions (21.40% vs. 75.00%, respectively, p=0.009; Fisher's exact test)." (PMID 34468540, 2021). "Amphiregulin (AR), a ligand of the epidermal growth factor receptor, enhances glutamine metabolism and supports cisplatin resistance in human chondrosarcoma by promoting NADPH production and inhibiting reactive oxygen species (ROS) accumulation." (PMID 37928274, 2023). "Amphiregulin expression was examined in 31 enchondromas and 67 chondrosarcomas using immunohistochemistry analysis." (PMID 34468540, 2021). "Furthermore, amphiregulin is reportedly expressed in mesenchymal tumors and is documented in chondrosarcomas in only four studies." (PMID 34468540, 2021). "Overall, 15 enchondromas (48.40%) and 24 chondrosarcomas (35.82%) were positive for amphiregulin." (PMID 34468540, 2021). "For instance, amphiregulin induces VEGF-A synthesis and angiogenesis in human chondrosarcoma via the FAK/c-Src pathway." (PMID 39247831, 2024). "Amphiregulin did not help in distinguishing enchondromas from low-grade chondrosarcomas." (PMID 34468540, 2021).
viral infection (8 papers, 2019 to 2025). "Upon stimulation by these cytokines, ILC2 produce IL-5, IL-9, IL-13, and amphiregulin (Areg), which are important effector molecules in responses to helminths in the intestine and promote repair of tissue damage caused by virus infections in the lung." (PMID 30770814, 2019). "Joller and colleagues show that the co-inhibitory receptor TIGIT induces the expression of the tissue growth factor amphiregulin (Areg) in regulatory T cells and contributes to tissue repair in response to viral infection." (PMID 41094201, 2025). "ILC2s have been reported to produce amphiregulin (Areg) to recover pulmonary epithelial integrity at viral infection." (PMID 34381446, 2021). "Moreover, ILC2s contribute to lung regeneration in the course of viral infections, and the amphiregulin (AREG) produced by ILC2s maintains the integrity of the airway and intestinal endothelium, which, in mouse models, results in reduced severity of influenza virus infection and reduced mortality." (PMID 38391948, 2024).
autoimmune disease (7 papers, 2017 to 2025). A disorder resulting from loss of function or tissue destruction of an organ or multiple organs, arising from humoral or cellular immune responses of the individual to their own tissue constituents. "In this review, we will discuss the current understanding of the structure, as well as the regulatory and functional features, of AREG, and its strategic role in the fibrotic process observed in several autoimmune diseases." (PMID 40868999, 2025). "The activation of the ADAM17/AREG axis has been demonstrated in various inflammatory conditions and in various autoimmune diseases, characterized by a chronic inflammatory state." (PMID 39768182, 2024). "The same probably account for the increased AREG expression in other autoimmune diseases like SLE, Sjogren’s syndrome, and RA, contrary to our data." (PMID 35058920, 2021). "The aim of this review is to evaluate emerging targeted interventions to modulate AREG-mediated molecular pathways in fibrotic processes observed in autoimmune diseases, starting with the structure of AREG and the molecular mechanisms in which the protein is involved." (PMID 40868999, 2025). "The epidermal growth factors amphiregulin (AREG) and heparin-binding epidermal growth factor (HB-EGF) are implicated in the pathogenesis of several autoimmune diseases, but their clinical and pathological roles in idiopathic inflammatory myopathy (IIM) are unclear." (PMID 34442026, 2021). "Together, these reports suggest that AREG and HB-EGF are related to the pathogenesis of autoimmune diseases and tissue fibrosis." (PMID 34442026, 2021).
chronic obstructive pulmonary disease (7 papers, 2010 to 2024). A chronic and progressive lung disorder characterized by the loss of elasticity of the bronchial tree and the air sacs, destruction of the air sacs wall, thickening of the bronchial wall, and mucous accumulation in the bronchial tree. "Elevated AREG expression is associated with airway inflammatory diseases, such as chronic obstructive pulmonary disease (COPD), asthma, and several types of cancer." (PMID 35379891, 2022). "AREG expression is mainly elevated in pathological conditions, such as cirrhosis and chronic obstructive pulmonary disease." (PMID 34671607, 2021).
Sepsis (7 papers, 2021 to 2025). Sepsis is defined as life-threatening organ dysfunction caused by a dysregulated host response to infection. "This analysis identified S100A, a gene encoding the tissue-protective growth factor amphiregulin, as consistently among the top 50 differentially expressed genes (DEGs) across all sepsis patients compared to control samples." (PMID 41303672, 2025). "Similarly, Das et al47 described dynamic changes in the blood immune profile during neonatal sepsis and identified plasma amphiregulin as a sepsis-associated inflammatory marker." (PMID 41147034, 2025). "AREG, which encodes amphiregulin, was among the downregulated genes in sepsis-induced ARDS." (PMID 35222683, 2022). "Amongst our findings, we identified amphiregulin as an early feature of the host immune response to sepsis and a plasma analyte that correlated with infection." (PMID 38195661, 2024). "Akin to our scRNA-seq analysis of CD3+ αβ-T cells, we observed that BATF and AREG were among the top differentially expressed genes within the B cell cluster during Enterobacter MCS versus its temporally closest pre-sepsis timepoint." (PMID 38195661, 2024). "Having identified AREG as an overarching DEG within PBMC at onset of sepsis or NEC, we next sought to understand its cellular source." (PMID 38195661, 2024). "Furthermore, extracellular AREG mediates sepsis in humans, and genes involved in the AREG-mediated pyroptosis signaling pathway were highly expressed in patients with severe sepsis compared with those with general or moderate sepsis." (PMID 40292295, 2025). "We recently discovered that the EGFR ligand, amphiregulin, could identify a cohort of infants with sepsis, even when CRP was low, identifying it as a potentially adjunctive biomarker for early infection." (PMID 41063987, 2025). "Given the capacity of these different leukocyte populations to readily produce robust quantities of amphiregulin within a four-hour in vitro stimulation window, we next hypothesized that amphiregulin might be elevated in the circulation during sepsis." (PMID 38195661, 2024). "Furthermore, single-cell RNA sequencing identifies upregulation of amphiregulin in leukocyte populations during sepsis, which we validate as a plasma analyte that correlates with clinical signs of disease, even when C-reactive protein is normal." (PMID 38195661, 2024). "Thus, we speculate that during preterm sepsis, early induction of amphiregulin might primarily mitigate against unchecked tissue damage, critical for preservation of developing organ integrity during early life." (PMID 38195661, 2024). "Subsequently, to assess whether plasma amphiregulin was raised in the context of sepsis, we examined amphiregulin levels over time in a cohort of 23 preterm babies who encountered one or more episodes of MCS or ClinSep, including 66 samples from 7 babies recruited from a different hospital cohort." (PMID 38195661, 2024). "AREG was highly expressed in the culture supernatant of LPS-stimulated THP1 cells and the serum of patients with sepsis." (PMID 40292295, 2025). "To first establish baseline levels in non-infected infants, we measured plasma amphiregulin in 9 babies (n = 23 samples) who did not encounter sepsis or NEC during their admission." (PMID 38195661, 2024). "There was no significant change in the ability of these different cell types to produce amphiregulin over the first 50 days of life again suggesting the dynamic expression of amphiregulin we have noted in sepsis is not related to age." (PMID 38195661, 2024). "Conspicuously, AREG was not upregulated in the baby in whom sepsis was captured three days after the blood culture was confirmed positive, suggestive that the kinetics of DEGs may vary dependent on stage of disease." (PMID 38195661, 2024).
Sepsis (continued). "Amphiregulin was the only analyte which could distinguish Sepsis samples with low or normal CRP from No-Sepsis samples, whereas amphiregulin, IL-6 and IL-10 could all distinguish No-Sepsis samples from Sepsis samples where CRP was elevated." (PMID 38195661, 2024). "Given that amphiregulin was dynamically elevated in some cases of sepsis without a CRP rise and vice versa, we hypothesized that development of a test for sepsis that combined both parameters would increase test accuracy to ‘rule-out’ sepsis." (PMID 38195661, 2024).
astrocytoma (6 papers, 2019 to 2025). "There are studies indicating that AREG plays a role in astrocytoma pathogenesis, which indicates the direction for future research of AREG as a tumorigenic factor and promising biomarker in astrocytomas." (PMID 36160033, 2022). "The last examined protein, OPN, is also better investigated as a potential astrocytoma marker than AREG and MMP-2." (PMID 33227903, 2020). "Amphiregulin (AREG), one of the ligands of epidermal growth factor receptor (EGFR) 3, has been observed in malignant astrocytoma 4–6 and is responsible for activating complex pathway networks, including Ras/MAPK, PI3K/Akt, PLC γ, and stat." (PMID 36160033, 2022).
liver cancer (6 papers, 2015 to 2026). An epithelial or non-epithelial malignant neoplasm that arises from the liver. "Our previously study suggested that EGF and AREG are abundant in human liver cancer." (PMID 28541302, 2017). "In addition, AREG is recognized as a therapeutic target for colon, pancreatic, liver cancer, and renal cell carcinoma 22,41." (PMID 25644309, 2015). "In our studies, we have suggested that locally elevated, aromatase-driven estrogen formation in human liver cancer tissues and cells may promote tumor cell growth through an estrogen-induced, ERα-mediated rise of AREG expression and the resulting activation of the EGFR signaling." (PMID 33925807, 2021). "We have reported that both AREG and ADAM17/TACE are expressed correspondingly with aromatase in liver tissues and liver cancer cell lines." (PMID 33925807, 2021). "To determine whether NK cell‐derived AREG impairs NK cell anti‐tumor activity beyond skin cancers, we tested AREG KO NK cells in NCG mice engrafted with two NK cell‐sensitive liver cancer cell lines, HepG2 and Huh7." (PMID 41082397, 2026). "In addition to the development of CRC, therefore, the Warburg effect regulated by AREG might be involved in the development of CRC as well as the development of pancreatic and liver cancer." (PMID 25644309, 2015). "Significantly, various known YAP/TEAD1 targeted genes, such as BIRC5, AREG, CCND1, CTGF, and MYC, were not activated through SRGN-mediated YAP signaling in liver cancer cell lines." (PMID 40384866, 2025).
lung adenocarcinoma (6 papers, 2016 to 2026). A carcinoma that arises from the lung and is characterized by the presence of malignant glandular epithelial cells. "Collectively, our findings suggest that pathologic downregulation of TSPX in NSCLC, especially in lung adenocarcinoma, results in upregulation of AREG, EREG, FOSL1, MYC, and PLAU, thereby potentiating the EGFR signaling pathway and leading to the initiation and/or exacerbation of cancer development." (PMID 39858622, 2025). "The expression levels of AREG, BIRC3, DKK1, EREG, FOSL1, MYC, and PLAU are negatively correlated with the survival ratio, and are significantly higher in the TSPX-low lung adenocarcinoma samples, compared to TSPX-high lung adenocarcinoma samples." (PMID 39858622, 2025). "Taken together, our results suggest that TSPX may suppress the development and/or progression of lung adenocarcinoma by downregulating AREG, BIRC3, DKK1, EREG, FOSL1, MYC, and PLAU, which could exacerbate lung adenocarcinoma, and upregulating the tumor suppressor CACNA2D2." (PMID 39858622, 2025).
myocardial infarction (6 papers, 2021 to 2025). Gross necrosis of the myocardium, as a result of interruption of the blood supply to the area, as in coronary thrombosis. "AREG is associated with several fibrotic diseases including cardiac fibrosis after myocardial infarction and cirrhotic cardiomyopathy." (PMID 39506618, 2024). "Recent evidence shows that these cells contain potent regenerative proteins, such as amphiregulin which can promote tissue repair through epidermal growth factor signalling and have been implicated in myocardial muscle repair post-myocardial infarction as well as wound healing." (PMID 39604770, 2025). "Amphiregulin has been shown to increase cardiac fibrosis and aggravate cardiac dysfunction in a mouse model of myocardial infarction." (PMID 35732465, 2022). "Previous studies have shown that AREG-positive Tregs preferentially accumulate in the heart following myocardial infarction (MI) compared to other tissues, such as the liver." (PMID 40495143, 2025). "Future studies will focus on elucidating whether AREG directly induces angiogenesis or acts indirectly by modulating pro-angiogenic factors such as VEGF and FGF, and further investigate the role of the complete signaling cascade, including AREG and FoxM1, in post-myocardial infarction angiogenesis." (PMID 40495143, 2025). "Stimulation of EGFR/ErbB receptors by amphiregulin (AR), another member of EGF family of ligands, induced cardiac fibrosis after myocardial infarction highlighting the detrimental role of EGFR/ErbBs in cardiac pathology." (PMID 34408653, 2021).
squamous cell carcinoma (6 papers, 2011 to 2022). A carcinoma arising from squamous epithelial cells. "Others have shown that HGF can stimulate release of the EGFR ligand amphiregulin in squamous cell carcinoma, a process dependent on the MAPK protein Erk2." (PMID 35325006, 2022). "A siRNA knockdown of Erk2 completely abolishes amphiregulin release in squamous cell carcinomas." (PMID 25884419, 2015). "In squamous cell carcinoma cells, amphiregulin is released by MMP cleavage." (PMID 21489260, 2011). "For example, Benjamin Kansy investigated the expression patterns of CD 44 and AREG, two signaling molecules essential for cell proliferation and differentiation, under the influence of selective TKIs in HPV+ and HPV- squamous carcinoma cell lines." (PMID 34722240, 2021). "In addition, AREG upregulated samples were enriched in the pathways of protein G-2 and S-phase expressed 1 (GTSE1) in G2/M progression after the G2 checkpoint, and associated with genes up-regulated in SCC12B2 cells (squamous cell carcinoma) by ultraviolet B (UV-B) irradiation." (PMID 33712015, 2021). "Furthermore, amphiregulin facilitates G-protein-coupled receptor (GPCR)-mediated transactivation of EGFR signaling and was shown to induce cellular proliferation and motility in squamous cell carcinoma." (PMID 29254206, 2017).
Stroke (6 papers, 2021 to 2025). Sudden impairment of blood flow to a part of the brain due to occlusion or rupture of an artery to the brain. "Five to seven days after the start of the stroke, Tregs infiltrate the brain parenchyma, drive microglial polarization toward the M2 phenotype, and inhibit astrocytic activation by blocking the Amphiregulin (AREG)/Epidermal Growth Factor Receptor (EGFR) pathway." (PMID 38808718, 2024). "In addition, Tregs can produce pro‐repair‐orientated cytokines, such as amphiregulin and osteopontin, which are neuroprotective following injuries such as stroke." (PMID 36975362, 2023). "Treg cells express high levels of amphiregulin (Areg) and OPN, which are thought to inhibit IL-6 and STAT3 pathways in microglia and astrocytes after stroke and reduce inflammation." (PMID 40289984, 2025).
cardiac hypertrophy (5 papers, 2021 to 2024). "According to a recent study AREG downregulation opposes cardiac hypertrophy through reduction of oxidative stress and apoptosis." (PMID 39506618, 2024). "On the other hand, Amphiregulin (AREG) produced by Ly6clow cardiac macrophages in cardiac tissue plays a crucial role in compensatory cardiac hypertrophy in a mouse model of pressure overload-induced HF." (PMID 38562923, 2024). "These outcomes showed that AREG downregulation weakened cardiac hypertrophy via attenuation of oxidative stress." (PMID 35996142, 2022). "In summary, this present study would probe the influences of AREG on cardiac hypertrophy and fibrosis, and quest whether AREG regulates cardiac hypertrophy through affecting oxidative stress and apoptosis." (PMID 35996142, 2022). "It remained to be further explored that AREG may be involved in the regulation of myocardial hypertrophy." (PMID 35996142, 2022). "The down-regulation of AREG could reduce myocardial hypertrophy by reducing oxidative stress and apoptosis." (PMID 35996142, 2022). "AREG downregulation reduced myocardial hypertrophy via inhibition of oxidative and apoptosis." (PMID 35996142, 2022). "Knockdown of AREG alleviated cardiac hypertrophy and fibrosis in mice heart with Ang II treatment." (PMID 35996142, 2022). "It has been reported that cardiac tissue macrophages are also involved in maintaining mitochondrial homeostasis, and that Amphiregulin (AREG), which is produced by Ly6clow cardiac macrophages, is important for compensatory cardiac hypertrophy in a murine pressure-overload heart failure model." (PMID 34745139, 2021). "AREG may be a target for future cardiac hypertrophy treatment." (PMID 35996142, 2022). "However, whether AREG participated in the regulation of cardiac hypertrophy is still unclear." (PMID 35996142, 2022). "As a result, Ly6Clow macrophages activated the amphiregulin-induced AKT/mTOR signaling pathway, and Ly6ClowMHCIIhigh macrophage polarization increased expression levels of osteopontin and TGF-β, which led to myocardial hypertrophy and fibrosis." (PMID 34135897, 2021).
fibrosis (5 papers, 2017 to 2025). the formation of excess fibrous connective tissue in an organ or tissue in a reparative or reactive process. "To determine the role of AREG in intestinal fibrosis, we established a DSS-induced chronic colitis model to induce intestinal fibrosis in both Areg−/− and WT mice." (PMID 40247299, 2025). "In particular, AREG has been reported recently to be upregulated in the urine of AKI and CKD patients and correlated with fibrosis." (PMID 28931758, 2017).
head and neck cancer (5 papers, 2007 to 2021). A primary or metastatic malignant neoplasm affecting the head and neck. "In various cancer types, including Head and neck carcinomas, Amphiregulin (AREG) overexpression has been involved in therapeutic failure and resistance to anti-EGFR therapies or to vincristine, a microtubule-destabilising agent." (PMID 34290392, 2021). "Interestingly, the corresponding proteins CCNA1, AREG or DDX20 have been individually found involved in a large range of solid tumours, including head and neck carcinoma." (PMID 34290392, 2021).